IL1B (interleukin 1 beta)
Diseases named in the same sentence as IL1B in open-access papers (continued):
Sharing a sentence is not in itself a finding about the gene and the disease.
diabetes (continued). "In the retina of mice with STZ-induced diabetes, Il-1β signal co-localized with ionized calcium-binding adapter molecule 1 (Iba-1), a microglial marker, mainly at the GCL, the site of predilection for retinal microglial cells activated by induction of diabetes to rats." (PMID 29170525, 2017). "Recent studies have suggested NLRP3 inflammasome/IL-1β pathway plays a critical role in the pathogenesis of type 2 diabetes mellitus, and other evidences have previously shown that sustained NLRP3 inflammasome activity contributes to impairing wound healing in diabetic mice." (PMID 28164132, 2017). "Therefore, diabetes-induced retinal AGE accumulation was suggested to activate IL-1β-related inflammatory cues in macrophages followed by Müller cells, linking to galectin-1 upregulation in human DR with time." (PMID 29170525, 2017). "NLRP3, caspase-1, IL-1β, and IL-18 were minimally expressed in normal glomerular tissues, but were significantly up-regulated in diabetic apoE (-/-) and apoE (-/-) mice, with more prominent changes in diabetes apoE (-/-) mice." (PMID 28708885, 2017). "Similarly, neutralizing IL-1β activity through the use of the IL-1 receptor antagonist is protective in multiple systems, including arthritis, diabetes, metabolic syndrome, psoriasis, periodic fevers, and gout among others." (PMID 28533778, 2017). "In PBMCs from children with diabetes, the gene expression microarrays identified that type 1 and type 2 DM likely shared a common pathway for β-cell dysfunction that includes secretion of IL-1β and prostaglandins by immune effector cells." (PMID 28900628, 2017). "In the groups of TB patients with impaired leukocyte ROS production, including the patients with diabetes mellitus, higher disease severity and poorer treatment outcome have been attributed to high levels of pro-inflammatory cytokines, including IL-1β, in the tissue." (PMID 29228045, 2017). "Particularly, since IL-1β has an important role in retinal microglia activation and proliferation under diabetes, limiting IL-1β-triggered inflammatory processes may provide a new therapeutic strategy to prevent the progression of diabetic retinopathy." (PMID 28588350, 2017). "Interestingly both hASC and hASC-CM were fully effective in reverting allodynia and restoring IL-1β, /IL-10 spinal cord balance also when injected 6 weeks after diabetes induction." (PMID 28851944, 2017). "Accordingly, IL-1β antagonist has been proposed as a promising therapeutic approach to diabetes." (PMID 26944557, 2016). "Canakinumab, a neutralizing antibody for IL1β, is under clinical trial for diabetes." (PMID 27229537, 2016). "There is a robust justification for blocking IL-1β in diabetes." (PMID 26953152, 2016). "In our model, Il1b gene expression was consistently upregulated by diabetes." (PMID 27942008, 2016). "In particular, interleukin-1β (IL-1β) has been involved in the pathogenesis of diabetes." (PMID 26944557, 2016). "In prediabetes and diabetes conditions, circulating levels of IL1β, IL18, and IL1RA, which are induced by IL1β, are elevated, and treatment with IL1β induces insulin resistance in adipocytes, implying that IL1β and IL18 have a crucial role in the development of type 2 diabetes." (PMID 27229537, 2016). "Because diabetes can affect the expressions of many cytokines related to immunity and inflammation, we examined uterine expressions of tumor necrosis factor α (TNFα) and interleukin 1β (IL-1β)." (PMID 26002932, 2015). "In contrast, others have failed to confirm an association between levels of IL-1β and diabetes in individuals with periodontal disease." (PMID 26211001, 2015). "Indeed, serum concentrations of IL-1β were found to be elevated in obese individuals, and correlated with insulitis and diabetes, while neutralization of IL-1β action via IL-1 receptor antagonist improves metabolic parameters in type 2 diabetes." (PMID 26516848, 2015).
diabetes (continued). "Bone marrow- derived macrophages was reported also contributed in IL-1β production in diabetes." (PMID 26394923, 2015). "Furthermore, increased basal IL‐1α and IL‐1β expression levels can lead to the development of the type 2 diabetes mellitus phenotype." (PMID 26660555, 2015). "The story may be further complicated during diabetes invivo during which macrophages recuited to the islet could increase IL-1β production." (PMID 25405767, 2014). "Moreover, the mRNA and protein levels of NLRP3 inflamamsome components and IL-1β achieved the highest levels at 8 or 12 weeks of diabetes except pro-IL-1β (all p<0.01)." (PMID 25136835, 2014). "We next aimed to study a possible role for enhanced circulating IL-1β in the observed diabetic endothelial dysfunction, determining its plasmatic levels in the streptozotocin-induced diabetic rats, as well as those of other pro-inflammatory cytokines, like TNF-α." (PMID 25518980, 2014). "The subgroup analyses showed that hypertension and diabetes may have some relevance with the gene expression of IL-1β and TNF-α." (PMID 25551602, 2014). "Intriguingly, the cardiac NLRP3 inflammasome and IL-1β expression in DM group were increased at 4 weeks, and reached to the highest levels at 8 or 12 weeks, and maintained at moderate high levels until 20 weeks of diabetes." (PMID 25136835, 2014). "It has been postulated that local secretion of low amounts of IL-1β by islet cells, has a vital role in the upholding of β-cell function, while lasting elevated pathological levels of IL-1β, feasibly produced by infiltrating immune cells, result in decreased β-cell function and mass in diabetes." (PMID 24594974, 2014). "Using a quantitative systems pharmacology modeling approach, we combined ex vivo data of IL-1β effects on β-cell function and turnover with a disease progression model of the long-term interactions between insulin, glucose, and β-cell mass in type 2 diabetes mellitus." (PMID 24918743, 2014). "Regarding the role of neutrophils in the initiation of the disease, one could expect that such IL-1β blockade at early ages may reduce the development of diabetes in NOD mice." (PMID 24968718, 2014). "Thus, blocking type I IFN signaling during diabetes partially but significantly restored the levels of IL-1α, IL-1β, IL-6, and CXCL10." (PMID 23533683, 2013). "Indeed, the results presented here demonstrate that blocking type I IFN signaling during diabetes partially yet significantly restored the levels of IL-1α, IL-1β, and IL-6." (PMID 23533683, 2013). "Consistent with relevance of this pathway in diabetes treatment, Il-1β, Nlrp3, and Asc gene expression is reduced after 1 year of weight loss in obese type 2 diabetic patients, and these gene expression changes were positively correlated with improvements in glycemia." (PMID 23483669, 2013). "Several observations support a role for IL-1β as a probable mediator of retinal damage in diabetes." (PMID 22615852, 2012). "Blockade of IL-1β signalling by administration of recombinant IL-1 receptor antagonist or neutralizing monoclonal antibodies has been shown to improve glycemic control in animal models of diabetes." (PMID 22922276, 2012). "We also found inverse associations between IL-1β and BC among individuals without diabetes, and it is unclear why increasing exposure would lead to decreasing IL-1β." (PMID 22336131, 2012). "Our findings point to IL-1β as a trigger and propagator of retinal neuroinflammation in diabetes." (PMID 22615852, 2012). "In insulin dependent diabetes mellitus (IDDM) various agents like interleukin-1 beta, interferon gamma, tumor necrosis factor alpha, alloxan and streptozotocin - could operate by forming free radicals that could attack the mitochondrial genome." (PMID 24250450, 2012). "Similarly varying results have been reported for the induction of both Il-1β and TNFα depending on the duration of diabetes." (PMID 21249158, 2011).
diabetes (continued). "This study highlights the importance to entertain caution while using tolerizing DC therapies that regulate islet autoantigen priming and prevent diabetes and that progression past the IL-1β/IL-17 checkpoint signals the need for adapting other tolerizing strategies." (PMID 22046502, 2011). "The aim of the present study was to evaluate if inhibition of the IKKβ and NFκB pathways could prevent 1) IL-1β mediated beta cell toxicity in vitro and 2) diet induced diabetes in vivo." (PMID 20948968, 2010). "Administration of curcumin inhibited diabetes-induced increase in inflammatory markers in the retina; the levels of IL-1β were significantly decreased in diabetic rats receiving curcumin (P < 0.05), and in the same retina the activation of NF-kB was also diminished." (PMID 17437639, 2007). "In diabetes-induced renal injury, caffeic acid protects renal function by reducing serum creatinine and blood urea nitrogen and inhibiting the production of inflammatory cytokines (such as IL-1β, IL-18, IL-6, and TNF-α) and the expression of NLRP3 inflammasome." (PMID 40909020, 2025). "Further, stimulation of skin cultures with TNF and IL-1β, but not with diabetes-associated factors like insulin and glucose, stimulate S100A8 and A9 expression in the skin, supporting the previous notion of an inflammatory-driven pathological overexpression of S100A8 and A9." (PMID 39337466, 2024). "Although the induction of Tregs and Th2 cytokine responses have been shown to improve diabetes, there is no direct evidence on whether they are associated with IL-1β." (PMID 39481080, 2024). "IL-1β has been recognized to be central in the development of complications for diabetes mellitus (DM)." (PMID 37762961, 2023). "In addition, aberrant macrophage pyroptosis and expression of IL-1β could be observed in periodontal lesions of rats with diabetes mellitus–periodontitis." (PMID 37047282, 2023). "Likewise, loss of periostin suppressed diabetes-triggered upregulations of the pro-hypertrophic genes (ANP, BNP, β-MHC), pro-fibrogenic genes (Col I, Col III, α-SMA), pro-inflammtory genes (IL-1β, IL-6, TNF-α) and pro-oxidative genes (NOX2, NOX4, 12-LOX) at the mRNA levels." (PMID 37993768, 2023). "Moreover, we also observed that the expression levels of NLRP3 and cleaved IL-1β were up-regulated in heart tissues of CD38flox mice with diabetes, but their expression levels were reduced in the CD38-deficient group compared with control mice under diabetes." (PMID 37958991, 2023). "Moreover, rosuvastatin could suppress NLRP3 inflammasome and IL-1β release in rats with type 2 diabetes and alleviate diabetes-induced cardiac dysfunction." (PMID 35017318, 2022). "Proinflammatory cytokines (IL-1β, IL-6) have multiple effects on many events including the initiation and maintenance of inflammation, endothelial dysfunction, metabolic syndrome, insulin resistance, diabetes mellitus, oxidative stress and cardiovascular events." (PMID 36326375, 2022). "IL-1β, a byproduct of pyroptosis, has been suggested to link periodontitis and systemic disorders; however, this has not been validated in diabetes-associated periodontitis." (PMID 36093182, 2022). "Additionally, the protective effect of N-acetylcysteine (NAC) in diabetes-related ocular surface damage may be attributed to inhibition of the ROS/NLRP3/Caspase-1/IL-1β pathway." (PMID 35656447, 2022). "However, treatment with Canakinumab, an IL1β inhibitor, did not reduce the risk of diabetes in patients with pre-diabetes." (PMID 35663964, 2022). "Upregulation of lncRNA Blnc1 expression could significantly decrease the levels of PTEN, cellulose, collagen I, collagen IV, inflammatory factors (TNF-α, IL-6, IL-1β) and ROS in HK-2 cells, inhibit the occurrence of ferroptosis, and alleviate the occurrence of diabetes and its complications." (PMID 36225311, 2022).
diabetes (continued). "Interestingly, the correlation analysis of gut microbiota with diabetes-induced intestinal inflammation showed that Deferribacteres were positively related to FBG, pro-inflammatory cytokines such as TNF-α, IL-1β, IL-6, and IL-17, which were negatively associated with IL-10 and TGF-β." (PMID 36045662, 2022). "Additionally, OPN with other reported inflammatory cytokines particularly IL-6, IL-8, IL-18, IL-1β, TNF-α, and serum CRP have been implicated in hypertension associated with diabetes via mediating the vascular effects of both angiotensin II (Ang II) and aldosterone, respectively." (PMID 34917685, 2021). "Furthermore, the IL-1β inhibitor, canakinumab, has been reported to reduce incident diabetes." (PMID 34356130, 2021). "In addition, treatment with the α-glucosidase inhibitor miglitol and barley lowered the expression of inflammatory cytokines, such as interleukin 1 beta and tumor necrosis factor alpha, and integrins, such as CD11s in peripheral leukocytes of rodents with diabetes." (PMID 34867790, 2021). "Therefore, in this study, we explored the role of IL-1β in diabetic wound closure using patient tissues and ex vivo fibroblast cultures and identified a novel mechanism behind delayed wound healing observed in patients with diabetes mellitus." (PMID 34054346, 2021). "However, a study combining anti-CD3 treatment with either Anakinra or an anti-IL-1β antibody resulted in reversal of diabetes in recent-onset T1D NOD mice, suggesting that combined therapy may also improve clinical efficacy in humans." (PMID 34177937, 2021). "However, the associations between IL1A and IL1B polymorphisms and IA were not significant after adjusting for age, smoking, drinking, diabetes, and hyperlipidemia status." (PMID 33511216, 2021). "Since P2X7 receptor is integral in the processing and release of many inflammatory mediators (IL-1β, NFκB, TNFα etc.), the inhibition of this receptor may provide therapeutic benefit in diseases including cancer, tuberculosis, diabetes, asthma, and all of the neurodegenerative diseases." (PMID 33889073, 2021). "However, the associations between IL1B polymorphisms and single IA were not significant after adjusting for age, smoking, drinking, diabetes, and hyperlipidemia status." (PMID 33511216, 2021). "In addition, circHIPK3 silencing alleviated mechanical hyperalgesia and thermal hyperalgesia in STZ-induced diabetes rats by inhibiting neuroinflammation through inhibiting the release of IL-1β, IL-6, IL-12, and TNF-α, indicating a close relationship between circHIPK3 and inflammation." (PMID 32318575, 2020). "The development of diabetes caused transcriptional activation of the mammalian target of rapamycin protein kinase gene, as well as increased mRNA expression of the pro-inflammatory cytokines IL1β and IL17A, but did not affect Foxp3 mRNA expression." (PMID 32341701, 2020). "Pathologically, inhibition of the TNF or IL-1β pathways may benefit patients with diabetes." (PMID 31427967, 2019). "In present study we also found the level of pro-inflammatory cytokines IL-1β and IL-6 in chronic diabetic rats were elevated, which was consistent with the opinion that inflammatory cytokines are involved in the pathogenesis of diabetes-related cognitive dysfunction." (PMID 30042685, 2018). "IL-1β mediates the IL-6 signaling pathway, and canakinumab, a fully human monoclonal antibody targeting IL-1β, leads to a marked reduction of both, plasma levels of IL-6 and CRP, without lowering the level of low-density lipoprotein (LDL) in patients with diabetes who were at high vascular risk." (PMID 29346331, 2018). "We speculate that sodium butyrate could relieve diabetes reflected by decreased level of IL-1β." (PMID 30410469, 2018).
diabetes (continued). "Since AGE has been shown to induce various inflammatory responses in diabetes, we checked two representative cytokines IL-6 and tumor necrosis factor (TNF)-α, both of which are classically known to be associated with the pathogenesis of DR, in addition to IL-1β." (PMID 29170525, 2017). "Although the primary outcome is based on the hypothesis that blocking IL-1β activity in these patients may also reduce the incidence in myocardial infarction and stroke, secondary end points include prevention and improvement of diabetes." (PMID 28659798, 2017). "Antioxidant supplementation by diosmin suppressed diabetes induced ROS resulting in deactivation of NF-κB associated pro-inflammatory chemokines and cytokines such as macrophage chemotactic protein (MCP-1), tumor necrosis factor (TNF-α), and interleukins (IL-1β and 6)." (PMID 27527213, 2016). "Issues that reduce the inflammation (particularly, key inflammatory markers such as pro-inflammatory mediators TNFα, IL-6, IL-1β and CRP) could offer a vital public health tool to reduce the burden of diabetes and associated complications including cardiovascular diseases in the general population." (PMID 27527213, 2016). "Similarly, IL-1β can be up-regulated in the retina in diabetes." (PMID 27649243, 2016). "Together, these findings indicated that IL-1β may play a key role to EC damage in diabetes." (PMID 26944557, 2016). "Applications of antagonists of IL-1β demonstrated significant therapeutic effects on diabetic cardiovascular complications both in experimental animals and human indicating that IL-1β played an important role in initiating and exacerbating cardiovascular complications of diabetes." (PMID 26394923, 2015). "Therefore, IL-1β plays an important role in the pathogenesis of diabetes." (PMID 26394923, 2015). "Growing evidence suggests that the inflammasome and the IL-1β/IL-18 axis play an integral part in the pathogenesis of many acute and chronic conditions, including gout, rheumatoid arthritis, atherosclerosis, Alzheimer’s disease, diabetes mellitus, and, most recently, oxalate crystal nephropathy." (PMID 24450291, 2014). "Moreover, our immunohistochemistry studies also revealed that sitagliptin was able to prevent the diabetes-induced increase in IL-1β and TNF-α mainly in the cells around the glomeruli, which are probably tubular cells and/or accumulation of interstitial inflammatory cells." (PMID 24817793, 2014). "Therefore, the lasting production of IL-1β, probably released by K. pneumoniae-activated Kupffer cells or neutrophils, might contribute to the enhancement of liver injury by diabetes." (PMID 24223208, 2013). "Because of the role that IL-1β can have in the development of retinal glial activation and endothelial dysfunction in diabetes, interrupting the vicious circle triggered by IL-1β autostimulation could be a mechanism to limit the progression of diabetic retinopathy." (PMID 22615852, 2012). "Thus, for those with diabetes, exposure to BC may especially affect IL-1β, which in turn may play a role in the elaboration of additional cytokines." (PMID 22336131, 2012). "Our analysis also showed that phloridzin specifically restored pathways regulated by interleukin-1 beta and nerve growth factor, the receptors for which and themselves are expressed by retinal glial cells, once more pointing out the role of Müller cells in the effects of phloridzin on diabetes." (PMID 22046295, 2011). "We have shown that intravitreal injection of interleukin-1β (IL-1β) to the normal rats increases retinal capillary cell apoptosis and histopathology; and these IL-1β-induced changes in the retinal capillaries of normal rats are similar to those observed in diabetes." (PMID 17437639, 2007). "It is also involved in the treatment of metabolic diseases, such as diabetes, inflammation, and cancer, by modulating signaling pathways (NF-κB, PI3K/AKT/mTOR, RAS/RAF) and inflammatory markers (IL-6, IL-1β, TNF-α)." (PMID 42282446, 2026).